SYK (spleen associated tyrosine kinase)
Diseases named in the same sentence as SYK in open-access papers (continued):
Sharing a sentence is not in itself a finding about the gene and the disease.
hepatocellular carcinoma (continued). "Some groups investigated the upstream of SYK in hepatocellular carcinoma, and the results indicated that SYK can be regulated by checkpoint kinase 1 (CHK1) effectively, and the phosphorylation of SYK induced by CHK1 enhances the subsequent proteasomal degradation of SYK in hepatocellular carcinoma." (PMID 36568669, 2022). "Using a schizophrenia-hepatocellular carcinoma network, the authors found that some schizophrenia candidate genes (SIRPB1, SYK, and LCK) and genes mediating the immune responses in the etiology mechanism of schizophrenia (IL-2 and TREM-1/DAP12) may also function as tumor-suppressor genes." (PMID 29254248, 2017).
lung carcinoma (8 papers, 2013 to 2024). "One study was performed to investigate the role of spleen tyrosine kinase (SYK) as an oncogenic driver in SCLC using weighted gene co-expression network analysis (WGCNA) based on lung cancer datasets." (PMID 38473324, 2024). "Consistently, in the in vivo xenograft model, compared to control mice, mice bearing MET-amplified EBC-1 lung cancer cells with stable SYK knockdown exhibited a significantly reduced response to the c-Met inhibitor INCB28060." (PMID 37183231, 2023). "A lower SYK protein expression and methylation are also connected with the metastasis of other cancer, including lung cancer, liver cancer, oral squamous cell cancer, pancreatic cancer, bladder cancer, gastric cancer, and urinary cancer." (PMID 34575665, 2021). "Hypermethylation of the SYK promoter leads to SYK silencing in human lung carcinoma and both are independent biomarkers of lung cancer development and metastatic spread." (PMID 31817924, 2019). "Spleen tyrosine kinase (SYK) takes an important role in angiogenesis, progression, and metastasis of lung cancer." (PMID 37279937, 2023). "The antitumor functions of FYN, SYK, and PTPN6 in lung cancer have been validated by previous research, which was consistent with our study." (PMID 37279937, 2023). "Therefore, diverse biological functions, such as immune recognition and inflammatory response, can be effectively regulated by SYK, and SYK is also considered as a novel therapy target in lots of non-hematopoietic diseases (e.g. liver fibrosis, lung cancer, and diabetic cardiomyopathy)." (PMID 36568669, 2022).
breast tumors (7 papers, 2008 to 2022). "Loss of SYK expression has been implicated in increased invasiveness and proliferation of breast tumors." (PMID 18959789, 2008). "Furthermore, our observations indicate a possible link between loss of SYK expression during breast tumor progression, loss of intercellular adhesion, and loss of control of mammary epithelial cell proliferation via the Hippo signaling pathway." (PMID 33670716, 2021). "The Hippo signaling pathway is involved in cell contact-mediated inhibition of proliferation, suggesting a possible link between loss of SYK expression during breast tumor progression, loss of intercellular adhesion, and loss of control of mammary epithelial cell proliferation." (PMID 33670716, 2021). "SYK has been reported to possess both tumour promotor and repressor activities and deletion has been linked to a pro-proliferative / pro-invasive phenotype in breast tumours." (PMID 32292575, 2020). "The identification of SYK activation pathways in mammary epithelial cells would allow completing the signaling network and better understanding its breast tumor suppressor function." (PMID 33670716, 2021). "In metastatic melanoma samples, SYK shows an increase in the abundance of the long form and a decrease of the short form, as previously observed in breast tumors." (PMID 27535130, 2016). "However, promoter analysis of TMPRSS2 and SYK using SMART App showed methylation of these promoters in breast tumor patient samples." (PMID 36474139, 2022).
Burkitt lymphoma (7 papers, 2018 to 2025). A rare form of malignant mature B-cell non-Hodgkin lymphoma. "In Burkitt lymphoma cells, the B-cell receptor signaling pathway was the most enriched in SYK targets, including the BTK protein tyrosine kinase." (PMID 33670716, 2021). "Our study links MYC to BCR signaling in Burkitt lymphoma through up regulation of SYK transcription by MYC and GCN5." (PMID 31645904, 2019). "Using Burkitt’s lymphoma-derived cells as a model for GC centroblasts, we showed that SYK inhibition decreased cell viability." (PMID 29740433, 2018). "Similar profiles for Mcl-1 and viability following SYK inhibition in the presence of Q-VD-Oph were observed with the Burkitt’s lymphoma cell lines RAMOS and BL2." (PMID 29740433, 2018). "Here, we comparatively evaluated the anti-tumorigenic effect of isoform-specific bivalent BET inhibitor AZD5153 and pan-BET inhibitor I-BET151 in a DLBCL and Burkitt’s lymphoma in vitro approach and further investigated the cell- and molecular effect of simultaneous SYK inhibition by Entospletinib." (PMID 36230614, 2022). "SYK inhibition lowers viability and Mcl-1 protein levels in Burkitt’s lymphoma cell lines." (PMID 29740433, 2018). "The platform uncovered known vulnerabilities (i.e. dasatinib in CML, HSP90 inhnhibitor in BL25) in parallel to uncovering new targets within a Burkitt lymphoma set (BTK and SYK in a subset of BL)." (PMID 30104685, 2018). "Here, we aimed to compare the anti-tumorigenic effect of a simultaneous SYK inhibition by Entospletinib with pan-BET inhibition by I-BET151 (I-BET) or isoform-specific bivalent BET inhibition by AZD5153 (AZD) in a DLBCL and Burkitt’s lymphoma in vitro approach." (PMID 36230614, 2022). "Similarly, overexpression of CEACAM1 in the CEACAM1-negative Burkitt lymphoma cell line ST486 did not affect the IgM surface expression but significantly downregulated SYK activation following BCR stimulation compared to control cells." (PMID 40436855, 2025).
colon carcinoma (7 papers, 2017 to 2024). "Next to the associations with tumor characteristics, we showed that high SYK(S) mRNA expression is associated with short HFS in our MATCH cohort of chemonaive LNN colon cancer patients." (PMID 28957395, 2017). "The dual role of SYK in epithelial cancers combined with the scarce literature on the role of SYK and its splice variants in colorectal cancer provided a rationale to assess their prognostic value in primary tumors of colon cancer patients." (PMID 28957395, 2017). "We aimed to assess the association of mRNA expression of overall SYK (SYK(T)) and its splice variants SYK(L) and SYK(S) with disease outcome in a well-defined homogeneous prospectively collected set of primary tumor tissues of patients with stage I-III colon cancer." (PMID 28957395, 2017). "Overall, a positive correlation was noticed between the overexpression of the SYK gene and the poor prognostic predictor for colon cancer." (PMID 34575665, 2021). "Next, we analyzed all cases of stage I-III colon cancer in the TCGA for which both the known CRC mutations and SYK(T) expression levels were available (n = 108)." (PMID 28957395, 2017). "In our cohort, we discovered SYK(S) as a significant prognostic marker for HFS for patients with untreated LNN colon cancer." (PMID 28957395, 2017). "The aim of this study was to explore the prognostic role of SYK in three cohorts of colon cancer patients." (PMID 28957395, 2017). "This association could however not be confirmed in two independent smaller cohorts, suggesting that further extensive validation is needed to confirm the prognostic value of SYK(S) expression in chemonaive LNN colon cancer." (PMID 28957395, 2017). "H3K36me2, expressions of multiple oncogenes (ADAM9, EGFR, Sox2, Bcl-2, SYK, and MET) and Akt activation were significantly decreased after NSD2 silencing or knockout in primary colon cancer cells." (PMID 34671018, 2021).
colorectal cancer (7 papers, 2012 to 2023). A primary or metastatic malignant neoplasm that affects the colon or rectum. "Further research is warranted to elucidate the role of SYK and its splice variants in colorectal cancer." (PMID 28957395, 2017). "In this study, we have characterized two SYK-independent activities associated with BAY61-3606 in colorectal cancer cells." (PMID 22815993, 2012). "Lastly, SYK is part of various prognostic gene signatures and the gene set used to define the consensus molecular subtypes of colorectal cancer." (PMID 28957395, 2017). "An onco-informatics analysis was adopted to evaluate the expression and prognostic value of the SYK gene in colorectal cancer (CRC), the third most fatal cancer type; of late, it may be a biomarker as another targeted site for CRC." (PMID 34575665, 2021). "The significance of SYK and its isoforms in colorectal cancer is largely unknown." (PMID 28957395, 2017). "Spleen tyrosine kinase (SYK) has been posed as marker predicting both poor and favorable outcome in various epithelial malignancies including colorectal cancer." (PMID 28957395, 2017). "Taken together, these results suggested that SYK was not the relevant target of BAY61-3606 in colorectal cancer cells expressing mutant K-RAS." (PMID 22815993, 2012).
Sepsis (7 papers, 2022 to 2026). Sepsis is defined as life-threatening organ dysfunction caused by a dysregulated host response to infection. "The analysis of these parameters (LDH, CK, creatinine, serum urea, ALT and AST) in CLP-mice treated with PRT062607 affirmed that the SYK inhibitor also reduced the renal dysfunction and hepatocellular injury caused by sepsis." (PMID 39559354, 2024). "Our results support the view that interventions which inhibit the activation of SYK are of potential therapeutic benefit in conditions associated with systemic (or local) inflammation including sepsis." (PMID 39559354, 2024). "Novel therapeutic strategies that inhibit SYK activity may be of benefit in patients with diseases associated with local or systemic inflammation including sepsis." (PMID 39559354, 2024). "Moreover, we investigated the mechanisms underlying the observed effects of the SYK-inhibitor by measuring the effects of sepsis in the absence and presence of the pharmacological intervention on serum cytokines and chemokines and the activation of key pro-inflammatory pathways in the heart." (PMID 39559354, 2024). "Spleen tyrosine kinase (SYK) expression was found to be higher in whole blood neutrophils and LDNs of patients with sepsis compared with healthy donors." (PMID 42012886, 2026). "Combined, these results establish LDNs as a heterogenous population of neutrophils that express high levels of SYK and support SYK inhibition as a potentially novel therapeutic target aimed at suppressing overactive neutrophils in sepsis." (PMID 42012886, 2026). "Here we show, for the first time, that the SYK inhibitor PRT062607 (15mg/kg administered at 1h after surgery) protects CLP-mice from sepsis-induced systolic and diastolic cardiac dysfunction of the right and left ventricle." (PMID 39559354, 2024). "Based on the results of our analysis, we identified SYK as a potential new target for sepsis-induced cardiac dysfunction and MOF." (PMID 39559354, 2024). "CLP-sepsis resulted in a significant increase in the phosphorylation and, hence, activation of SYK in cardiac tissue, which was inhibited by the administration of PRT062607." (PMID 39559354, 2024). "This study reports for the first time that inhibition of SYK-activation reduces cardiac dysfunction and, hence, ameliorates renal dysfunction and hepatocellular injury in a clinically relevant murine model of sepsis." (PMID 39559354, 2024). "In order to gain a better insight into the potential mechanism of action of PRT062607, we investigated the effects of sepsis (in the absence or presence of drug treatment) on a) the activation of the target, SYK, and b) pivotal pro-inflammatory pathways activated during sepsis." (PMID 39559354, 2024). "Notably, the MSS remained below 2 in CLP-mice treated with PRT062607, providing additional confirmation of reduction by SYK inhibition of the key clinical signs of sepsis." (PMID 39559354, 2024). "Taken together, our findings show that PRT062607 is a potent small molecule, which inhibits the activation of the SYK-NF-κB axis, which in turn is a key player in the inflammatory response during sepsis and, hence, in sepsis-induced cardiac and organ dysfunction." (PMID 39559354, 2024). "The preservation of the cardiac function afforded by the SYK inhibitor PRT062607 was also associated with a protective effect against the development of hypothermia and bradycardia, both of which are common clinical signs of septic shock in patients with sepsis." (PMID 39559354, 2024). "Indeed, when compared to healthy volunteers, the SYK gene is highly expressed in post-operative patients diagnosed with septic shock, and this may contribute to the pathophysiology of sepsis and, hence, cardiac dysfunction and MOF." (PMID 39559354, 2024).
Sepsis (continued). "Functionally, the SYK inhibitor R406 suppressed changes in neutrophil features of activation from normal-density neutrophils and LDNs, including the SYK+ and SYK- neutrophil subsets, and MPO release from LDNs following LPS stimulation of sepsis neutrophils." (PMID 42012886, 2026). "What, then, is the mechanism(s) by which the SYK-inhibitor PRT062607 reduces the cardiac dysfunction and MOF in murine sepsis?" (PMID 39559354, 2024). "In order to address this hypothesis, we subsequently investigated the effects of a novel, highly selective SYK inhibitor, PRT062607 (or P505-15), on myocardial (dys)function and MOF in a clinically relevant, murine model of sepsis." (PMID 39559354, 2024). "Thus, we investigated the effects of the highly selective SYK inhibitor PRT062607 (15mg/kg; i.p.)on sepsis-induced cardiac dysfunction and MOF in a clinically-relevant, murine model of sepsis." (PMID 39559354, 2024). "Interestingly, SYK takes part in TLR4 signaling, and in the activation of the NF-κB pathway and the NLRP3 inflammasome, which are known to be crucial players in the pathophysiology of sepsis." (PMID 39559354, 2024). "The upregulation of FcγR‐related genes, such as FCGR3A, FCGR1A, LYN, SYK, FYN and SRC, was detected in the prefrontal cortex, hippocampus, heart and colon of our sepsis patients, but not in the kidneys or lungs." (PMID 37731199, 2023).
T-cell lymphoma (7 papers, 2006 to 2022). "SYK, for example, has been implicated in the pathogenesis of B-cell and T-cell lymphomas and certain myeloid malignancies such as myelodysplastic syndrome (MDS) and AML." (PMID 26315286, 2015). "Only SYK was down-regulated (log2 fold-change −2.7) and BTK showed a borderline non-significant tendency towards down-regulation (log2 fold-change −2.0) in probable T-cell lymphomas." (PMID 29674676, 2018).
acute lymphoblastic leukemia (6 papers, 2014 to 2023). Leukemia with an acute onset, characterized by the presence of lymphoblasts in the bone marrow and the peripheral blood. "In precursor B-acute lymphoblastic leukemia (B-ALL), the pathogenic role and therapeutic potential of SYK is still controversially discussed." (PMID 33435587, 2021). "Indeed, defective SYK expression has been implicated in the pathogenesis of infant pro-B cell acute lymphoblastic leukemia (ALL), which is thought to originate from B-cell precursors with a maturational arrest at the pro-B cell stage and is associated with poor prognosis." (PMID 25506060, 2014).
Autoimmunity (6 papers, 2011 to 2025). The occurrence of an immune reaction against the organism's own cells or tissues. "SYK plays an important role in regulation of innate immunity and inflammatory response, and is involved in several human diseases such as allergy, autoimmunity, and haematological malignancies (reviewed by Mócsai et.al)." (PMID 21693067, 2011). "Fostamatinib is an oral SYK inhibitor initially developed for autoimmune conditions." (PMID 41050133, 2025). "Thus, as proposed and shown by Duggan et al40, SYK inhibitors, such as fostamatinib, that conventionally target B-cell–driven autoimmune conditions, were capable of inhibiting both STAT and SYK action in EAC cells that reduced their growth." (PMID 35123116, 2022).
depression (6 papers, 2011 to 2025). "Isoglycyrrhizin, a flavonoid similar to quercetin, has recently been demonstrated to improve depression by inhibiting NLRP3-mediated cellular pyroptosis via the miRNA-27a/SYK/NF-κB axis." (PMID 35369029, 2022). "Lipopolysaccharide and chronic social defeat stress models of depression were established to examine the impact of isoliquiritin on depressive behaviors, hippocampal miRNA-27a/SYK/NF-κB cascade and NLRP3-regulated pyroptosis." (PMID 33402173, 2021). "The miRNA-27a/SYK/NF-κB axis was also involved in depression." (PMID 33402173, 2021). "Similarly, in MDD patients and in LPS or chronic social defeat stress (CSDS)-induced depression models in mice, the use of Isoliquiritin upregulated miRNA-27a expression and downregulated SYK expression, thereby protecting microglia from pyroptosis and alleviating MDD symptoms in mice." (PMID 35937897, 2022). "These genes included SBNO2, CEACAM5, AKAP1, UBC, ACTB, UBB, and FOS for schizophrenia; SEC24C, PGLYRP1, ARHGAP4, RPL22, SLC6A11, and SYK for bipolar disorder; and SRRT, PARK2, LILRA4, STK17A, IGFBP2, and NF1 for major depression." (PMID 22373040, 2011).